POGLUT3 (protein O-glucosyltransferase 3)
Description:
Protein glucosyltransferase that catalyzes the transfer of glucose from UDP-glucose to a serine residue within the consensus sequence peptide C-X-N-T-X-G-S-F-X-C. Can also catalyze the transfer of xylose from UDP-xylose but less efficiently. Specifically targets extracellular EGF repeats of proteins such as NOTCH1, NOTCH3, FBN1, FBN2 and LTBP1. May regulate the transport of NOTCH1 and NOTCH3 to the plasma membrane and thereby the Notch signaling pathway.
Synonyms: KDELC2; MGC33424
Tractability: Antibody: UniProt predicts a signal peptide or a membrane-spanning region. PROTAC: ubiquitination databases record sites on it.
Gene: Protein-coding gene on chromosome 11 (108,472,112 to 108,498,405, reverse strand). Ensembl gene ENSG00000178202.
Subcellular location: Endoplasmic reticulum lumen
Subcellular location (Human Protein Atlas): Nucleoplasm; Vesicles
Gene Ontology:
Molecular function: EGF-domain serine glucosyltransferase activity; EGF-domain serine xylosyltransferase activity; UDP-glucosyltransferase activity; UDP-xylosyltransferase activity; glucosyltransferase activity
Biological process: protein O-linked glycosylation via glucose
Cellular component: endomembrane system; endoplasmic reticulum lumen
Genetic constraint (gnomAD): Loss-of-function variants: 39 observed, 42.42 expected, observed/expected ratio (o/e) 0.92, 90% interval 0.71 to 1.2. The upper end of that interval is the gene's LOEUF score, 1.2, which puts it in group 5 of 6, group 1 being the genes least tolerant of losing a copy. Missense variants: 589 observed, 559.68 expected, observed/expected ratio (o/e) 1.05, 90% interval 0.98 to 1.13. Synonymous variants: 203 observed, 207.89 expected, observed/expected ratio (o/e) 0.98, 90% interval 0.87 to 1.1.
Homologues: Orthologues: chimpanzee POGLUT3 (99% identical), rabbit POGLUT3 (91% identical), pig POGLUT3 (91% identical), dog POGLUT3 (90% identical), guinea pig POGLUT3 (87% identical), rat Poglut3 (86% identical), mouse Poglut3 (85% identical), tropical clawed frog poglut3 (73% identical), zebrafish poglut3 (65% identical). Paralogues in human: POGLUT2 (52% identical), POGLUT1 (23% identical).
Diseases named in the same sentence as POGLUT3 in open-access papers:
POGLUT3 is named in the same sentence as 29 diseases in open-access papers, as found by Europe PMC text mining. Sharing a sentence is not in itself a finding about the gene and the disease. The quoted sentences say what the papers report.
breast carcinoma (4 papers, 2017 to 2024). "Additionally, replication in UKBB and Finngen was observed for other results, including PLAUR [breast cancer OR: 1.82, 95% CI: 1.37 to 2.42], POGLUT3 [kidney cancer OR: 0.72, 95% CI: 0.60 to 0.88], and CTRB1 [pancreas cancer OR: 0.83, 95% CI: 0.75 to 0.92]." (PMID 38684708, 2024).
prostate carcinoma (3 papers, 2023 to 2024). A carcinoma that arises from epithelial cells of the prostate gland. "The same SNP is also linked to increased risk of breast, renal and prostate cancer suggesting that POGLUT3 protein stability is a risk factor for cancer." (PMID 38854010, 2024).
autism (1 paper, 2024). Persistent deficits in social interaction and communication and interaction as well as a markedly restricted repertoire of activity and interest as well as repetitive patterns of behavior. "Four Qualifying variants in B1 genes (with published indirect association with autism) were identified in four subjects, in the following genes: BRPF3, GTF2A1, POGLUT3, and TMEM184B, including a de novo loss-of-function variant in POGLUT3." (PMID 38256266, 2024).
bladder cancer (1 paper, 2024). "Among these, two also associated at nominal significance with ovarian cancer (TLR1 and PDCD6), one also associated with lung cancer (POGLUT3) and one associated with each kidney (POGLUT3), and bladder cancer (LAYN)." (PMID 38684708, 2024).
Hypertension (1 paper, 2022). The presence of chronic increased pressure in the systemic arterial system. "However, changes in Poglut3 expression can affect multiple pathways, and therefore Poglut3 might contribute to the pathophysiology of hypertension in several ways." (PMID 34929167, 2022).
kidney cancer (1 paper, 2024). Primary or metastatic malignant neoplasm involving the kidney. "TNFRSF10B and POGLUT3 associated with kidney cancer and were also associated with other malignancies." (PMID 38684708, 2024). "POGLUT3 was associated with a lower risk of kidney cancer [OR: 0.71, 95% CI: 0.63 to 0.79; PP4: 0.98] and lung adenocarcinoma [OR: 0.80, 95% CI: 0.73 to 0.89; PP4: 0.99] but an increased risk of both ER- and triple-negative breast cancer." (PMID 38684708, 2024).
muscular dystrophy (1 paper, 2025). Muscular dystrophy (MD) refers to a group of more than 30 genetic diseases characterized by progressive weakness and degeneration of the skeletal muscles that control movement. "MiR-195 also regulates POGLUT3, a gene implicated in muscular dystrophy." (PMID 40559391, 2025).
POGLUT3 also shares sentences with these, for which no sentence is quoted: cancer (5 papers); glioblastoma (5); glioma (3); melanoma (2); tumor (2); Uterine leiomyoma (2); arthrosis (1); aspergillosis (1); astrocytic tumor (1); astrocytomas (1); cervical spondylosis (1); chalazion (1); insulin-dependent diabetes mellitus (1); lung adenocarcinoma (1); lung carcinoma (1); mantle cell lymphoma (1); ovarian carcinoma (1); pancreas cancer (1); pneumonia (1); renal cell carcinoma (1); Stroke (1); triple-negative breast carcinoma (1).